RETREG3 (reticulophagy regulator family member 3)
Description:
Endoplasmic reticulum (ER)-anchored autophagy regulator which exists in an inactive state under basal conditions but is activated following cellular stress. When activated, induces ER fragmentation and mediates ER delivery into lysosomes through sequestration into autophagosomes via interaction with ATG8 family proteins. Promotes ER membrane curvature and ER tubulation required for subsequent ER fragmentation and engulfment into autophagosomes. Required for collagen quality control in a LIR motif-dependent manner (By similarity). Mediates NRF1-enhanced neurite outgrowth.
Synonyms: FAM134C; DKFZp686B1036; FLJ33806
Tractability: Antibody: UniProt predicts a signal peptide or a membrane-spanning region. PROTAC: ubiquitination databases record sites on it.
Gene: Protein-coding gene on chromosome 17 (42,579,513 to 42,610,623, reverse strand). Ensembl gene ENSG00000141699.
Subcellular location: Endoplasmic reticulum membrane
Subcellular location (Human Protein Atlas): Nuclear membrane; Nucleoplasm; Cytosol
Gene Ontology:
Molecular function: protein binding; endoplasmic reticulum-autophagosome adaptor activity
Biological process: endoplasmic reticulum tubular network organization; positive regulation of neuron projection development; reticulophagy; substrate localization to autophagosome
Cellular component: endoplasmic reticulum membrane; endoplasmic reticulum tubular network; protein-containing complex; endoplasmic reticulum
Genetic constraint (gnomAD): Loss-of-function variants: 22 observed, 46.78 expected, observed/expected ratio (o/e) 0.47, 90% interval 0.34 to 0.67. The upper end of that interval is the gene's LOEUF score, 0.67, which puts it in group 2 of 6, group 1 being the genes least tolerant of losing a copy. Missense variants: 546 observed, 612.58 expected, observed/expected ratio (o/e) 0.89, 90% interval 0.83 to 0.96. Synonymous variants: 240 observed, 239.64 expected, observed/expected ratio (o/e) 1, 90% interval 0.9 to 1.12.
Homologues: Orthologues: chimpanzee RETREG3 (99% identical), macaque RETREG3 (98% identical), rabbit RETREG3 (94% identical), dog RETREG3 (93% identical), pig RETREG3 (93% identical), mouse Retreg3 (91% identical), rat Retreg3 (91% identical), guinea pig RETREG3 (86% identical), tropical clawed frog retreg3 (63% identical).
Diseases named in the same sentence as RETREG3 in open-access papers:
RETREG3 is named in the same sentence as 6 diseases in open-access papers, as found by Europe PMC text mining. Sharing a sentence is not in itself a finding about the gene and the disease.
RETREG3 shares sentences with these, for which no sentence is quoted: cancer (2 papers); infection (2); bacterial infection (1); breast carcinoma (1); neuroblastoma (1); Obesity (1).